TNF (tumor necrosis factor)
Diseases named in the same sentence as TNF in open-access papers (continued):
Sharing a sentence is not in itself a finding about the gene and the disease.
anemia (continued). "Ibrutinib generally improves anemia and gives prolonged disease control while ruxolitinib caused significant anemia, potentially from increases in TNFα that can suppress erythropoiesis, and had little therapeutic activity during the time it was administered to patients." (PMID 37114129, 2023). "All patients with pulmonary tuberculosis as well as patients with extrapulmonary tuberculosis were included as subjects and a clinical severity score based on anemia, weight loss, presence of hypoxia, and radiological features was calculated and compared with TNF-α levels." (PMID 37007342, 2023). "A high TNF production is associated with accelerated parasite clearance, while excessive TNF levels are associated with complications such as cerebral malaria or severe anemia." (PMID 37215099, 2023). "Whether anemia itself is directly causing a boost in TNF production or if augmented inflammation is leading to the establishment and/or persistence of anemia cannot be determined with our data and warrants further mechanistic investigations." (PMID 35812431, 2022). "Alternatively, cytokines such as IL-6, IL-1 and TNF-alpha and metabolites associated with anemia of chronic disease could modulate monocyte function and lead to an upregulation of PD-1." (PMID 35625643, 2022). "Here, the reduced anemia could be associated with the high serum levels of IL-10, and IL-12 and the deficiency of TNF-α, IFN-γ and MIF." (PMID 36093199, 2022). "It is widely acknowledged that low grade inflammation and chronic disease is associated with anaemia and that several pro-inflammatory cytokines, such as IL-6 and tumor necrosis factor-α (TNF-α) could inhibit erythropoiesis and the actions of erythropoietin." (PMID 33781199, 2021). "Conversely, TNF-RI protects against fetal anemia and might do so by binding and neutralizing TNF-α, an inflammatory cytokine that has been associated with anemia." (PMID 33995348, 2021). "The most commonly reported adverse effects were hematological (especially leukopenia, as well as thrombocytopenia and anemia), fatigue, fever, hypotension (this was transitory and treated with vasopressors, associated in some studies with TNF-α leaks), and the mild elevation of myoglobin." (PMID 34771649, 2021). "TNF-α causes anemia by inhibiting erythroid-precursor proliferation and promoting hypoferremia." (PMID 32994531, 2020). "Anemia and prior CD surgery have been linked to loss of anti-TNF response." (PMID 33237166, 2020). "Cancer-related anemia is a common complication for cancer patients because of chromic blood loss, iron deficiency, vitamin deficiency and inflammation imbalance in terms of increased expression of interleukin and tumor necrosis factor." (PMID 29335609, 2018). "The importance of host-derived factors such as TNF-α in acute anemia development was further substantiated by the observation that T. brucei-infected TNF-α-deficient (TNF-α−/−) mice exhibited greatly reduced acute anemia levels compared with control WT mice." (PMID 29497418, 2018). "The low IL10/TNFα ratio has been associated with severe anemia in young children." (PMID 27034825, 2016). "This SNP has previously been associated with iron deficiency as part of a haplotype together with other TNF SNPs, as well as with an increased risk of severe anemia in low-birth-weight children in Kenya and increased risk of severe malarial anemia in Gambian children." (PMID 27332551, 2016). "In clinical studies of children with malarial anemia, the proportion of circulating monocytes containing hemozoin and levels of plasma hemozoin were associated with anemia and reticulocyte suppression, independently of the level of circulating cytokines, including TNF-α." (PMID 25781011, 2015). "Moreover, a GPI-based intervention strategy was found to alleviate trypanosomosis-associated anemia development by lowering the proinflammatory cytokine production (including TNF, MIF, and Gal-3) and increasing IL-10 production." (PMID 26090446, 2015).
anemia (continued). "Though recent studies have found that an increase in serum hepcidin in active RA patients was associated with elevated serum IL-6 and TNF-α levels, the role of hepcidin and its regulation by cytokines in the pathogenesis of RA-anemia is still largely unknown." (PMID 24286116, 2013). "Obviously, TNFα causes anemia independently of inhibition of Epo production." (PMID 20204172, 2009). "Nevertheless, the capacity of both TNF and hemozoin to depress erythropoiesis by inducing apoptosis has not been consensually demonstrated in vitro and apoptosis was not implicated in impaired maturation of erythroblasts during anemia of experimental P. chabaudi infection." (PMID 28018860, 2016). "Potential mechanisms of trichuris-related anemia include worm consumption of blood in the context of heavy infections, colonic lesions with associated bleeding, or chronic reduction in food and micronutrient intake due to the anorexia inducing effects of TNF-alpha released in response to infection." (PMID 21738863, 2011). "Here, we infer that strain-directed immunomodulation contributes to differences in anemia severity, with pro-inflammatory cytokines IL-1β, IL-6, IFN-γ, and TNF-α implicated." (PMID 41602558, 2026). "Treatment-induced tissue damage elevates circulating mediators (C-reactive protein [CRP], IL-6, interleukin-1β [IL-1β], interferon [IFN], tumor necrosis factor-α [TNF-α] potentially mediating central fatigue through anemia and cachexia pathways." (PMID 40496975, 2025). "CRP production (primarily regulated by IL-6 and indirectly by TNF-α) and TNF-α’s direct suppression of erythrocyte progenitor cell proliferation both contribute to anemia." (PMID 41179861, 2025). "Salivary cytokines showed distinct profiles, with elevated levels of TNF-α in anaemia and IL-8 in patients with diarrhoea." (PMID 40545713, 2025). "Simultaneously, tumor necrosis factor-alpha suppresses erythroid progenitor differentiation in the bone marrow and diminishes erythropoietin responsiveness, further exacerbating anemia." (PMID 40687061, 2025). "Chronic inflammation, typical of RA, facilitates the onset of anemia via increased concentrations of pro-inflammatory cytokines, including TNF-α and IL-6." (PMID 40385581, 2025). "Studies have shown that the severity of anemia in TB patients can correlate with markers of disease activity, such as elevated inflammatory cytokines (e.g., interleukin 6 (IL-6) and tumor necrosis factor alpha (TNF-α)) and C-reactive protein (CRP) levels." (PMID 40698207, 2025). "Oxidative stress disrupts tight junction proteins such as occludin and claudin, leading to increased BBB permeability.Anemia and ischemia activate microglia and astrocytes, releasing pro-inflammatory cytokines (e.g., TNF-α, IL-1β) and chemokines." (PMID 40486649, 2025). "Sb showed superiority in reducing anemia and TNF-α and elevating CD4 and DRD1 gene expression and improving brain histopathological alteration compared to dark chocolate." (PMID 40615531, 2025). "Anemia can stimulate the production of pro-inflammatory cytokines such as tumor necrosis factor-alpha (TNF-α), interleukin-1 beta (IL-1β), and interleukin-6 (IL-6)." (PMID 40486649, 2025). "As a possible molecular pathomechanism for anemia in low-risk MDS, a pro-apoptotic niche with increased activity of apoptosis-promoting factors such as tumor necrosis factor (TNFα) and pro-apoptotic Fas ligand (CD95L) have been proposed." (PMID 38413410, 2024). "Proinflammatory cytokines like interferon (IFN), tumor necrosis factor (TNF), macrophage migration inhibitory factor, and hemozoin have been linked to the pathogenesis of haemolysis and anaemia during malaria infection, according to a number of studies." (PMID 38566916, 2024). "Infiltration of parasitized cells in bone marrow crowds out progenitor cells and shift the cytokine environment by favoring production of inflammatory cytokines, such as TNF and IFNγ, that inhibit erythropoiesis, which can result in anemia." (PMID 39514579, 2024).
anemia (continued). "The administration of an anti-TNFα monoclonal antibody lowers anemia levels in human TNFα transgenic mice, by reducing the apoptotic erythroblasts." (PMID 38731114, 2024). "The role of TNFα in triggering apoptosis is supported by a research report that discovered a positive correlation between elevated serum TNFα levels and anemia in MDS patients." (PMID 37990142, 2023). "As an example, MDSCs are capable to induce anemia, through their production of TNF‐α: the main cytokine regulator of erythropoiesis." (PMID 36524315, 2023). "Because elevation of TNFα also occurs in sterile inflammation, elevation of HAMP will increase the risk of iron-deficiency anemia." (PMID 39619227, 2023). "The results of the ROC and OR analysis of age and inflammatory variables, i.e., IL-1β, TNFα and HPC, indicate a potential diagnostic value for clinical prognosis for patients with age-associated anemia." (PMID 37240288, 2023). "This increase in TNFα showed a positive correlation with clinical anemia, and an elevated rate of apoptosis in the early stages of MDS." (PMID 37990142, 2023). "A pooled analysis from three large randomized clinical trials reported a better response to anti-TNF (infliximab + MTX) in terms of normalization of Hb levels in RA patients with anemia at baseline." (PMID 37237405, 2023). "Another 5 markers were only related to clinical disease severity and anemia including sCD30, IL-8, IL-20, IL-29/IFNδ1 and TNF-α." (PMID 38162636, 2023). "We further analysed circulating tumour necrosis factor‐α (TNF‐α) and interferon‐γ (IFN‐γ) levels in the patient's serum to determine possible causes of postoperative anaemia." (PMID 35846224, 2022). "The cytokine-induced inhibition of erythropoiesis is regarded as an important mechanism for the development of anemia in cancer patients, TNFα in particular but also other inflammatory regulators, including IL1β, IL6, IL10 and IFNγ, probably contribute." (PMID 35160156, 2022). "Moderate anemia (8-10 g/dl) was identified in both RA-DMARDs (5 cases) and RA patients treated with anti-TNFα therapy (GOL- 1 case; ADA- 3 cases; ETA- 2 cases)." (PMID 35651659, 2022). "It has been shown that the increase expression of TNFα can stimulate hepcidin generation, and the application of TNFα inhibitors can reduce hepcidin production and improve anemia." (PMID 36335331, 2022). "Proinflammatory cytokines, including tumor necrosis factor (TNF)-alpha, interleukin (IL)-1, IL-6, and IL-10, play important roles in RA-associated anemia." (PMID 36008838, 2022). "An analysis of the Rhumadata® clinical database and registry confirmed that the improvement in anemia observed with IL-6 inhibitors was “numerically and statistically superior” to TNF inhibitors." (PMID 36008838, 2022). "Systemic inflammation, mediated by inflammatory cytokines such as tumor necrosis factor-alpha (TNF-α), interleukin-1 (IL-1), interleukin-6 (IL-6), and interferon- (IFN- γ), is a well-known cause of anemia." (PMID 35984839, 2022). "Other cytokines, including TNF-α, IL-1, and IL-6, lead to the expansion of CECs and enrichment of early-stage CECs by impairing erythropoiesis and aggravating anemia." (PMID 35251018, 2022). "Linking this information to our results in anemic participants, we can infer that in PWH with anemia, there is an exacerbation of TNF production." (PMID 35812431, 2022). "Inflammatory cytokines secreted by tumors, such as IL-6 and TNF-α, can change the tumor and hematopoietic microenvironment, leading to worsening tumor oxygenation and tumor-related anemia." (PMID 34208273, 2021). "Laboratory investigation indicated mild anaemia and elevations of leucocytes, interleukin 1 beta, tumor necrosis factor alpha." (PMID 34847873, 2021). "Serum iron was decreased in 46% of patients before the initiation of anti-TNF therapy, consistent with the anemia of inflammatory disease." (PMID 35095905, 2021).
anemia (continued). "Maternal anemia was also associated with cytokine responses in cord (particularly for MDP and LPS), with higher IL-10, IL-1β, MDC, TNF, IL-12p70, IL-12p40 responses following PRR stimulation." (PMID 32765436, 2020). "Limited data in patients with RA suggest that the IL-6 receptor blocker tocilizumab was more effective than TNF-α inhibitors in improving anaemia of chronic disease and normalizing iron metabolism via inhibition of hepcidin." (PMID 32264972, 2020). "On anti-TNFα treatment > 5% of patients reported infection (8 patients; 14.0%), nausea (4 patients; 7.0%), anemia (4 patients; 7.0%), arthralgia (3 patients; 5.3%) and eczema (3 patients; 5.3%)." (PMID 32640990, 2020). "Previous studies have evaluated the therapeutic effect of TNF blockers on hemoglobin levels and anemia in IBD patients." (PMID 32640680, 2020). "On the other hand, it has been shown that the prevalence and severity of anemia are related to IBD activity and treatments used to attenuate the IBD-associated mucosal inflammation (i.e., TNF blockers) can improve ACD." (PMID 32640680, 2020). "Previous work has demonstrated that TNF-α induces the anemia in IBD patients by weakening absorption of iron, while anti-TNF-α therapy improves anemia in CD patients and is associated with the decreased levels of serum hepcidin." (PMID 31814801, 2019). "It not only explores relevant mechanisms but also emphasizes the importance of the application of anti-TNF-α therapy in the management of anemia of IBD." (PMID 31814801, 2019). "Increased concentrations of TNF are associated with high placental parasite density and pregnancy complications such as LBW, IUGR, preterm birth and maternal anemia." (PMID 30930847, 2019). "IL-10 suppresses inflammation by suppressing various cytokines, including IL-1β and TNFα, which is also a mechanism involved in down-regulating hepcidin expression and alleviation of anemia." (PMID 30836628, 2019). "For example, in Trypanosoma brucei infection, anemia is in part caused by nitric oxide (NO) production, and pro-inflammatory cytokines, such as IFNγ and TNF positively correlate with anemia severity." (PMID 30619317, 2018). "When adjusted for maternal anemia (as a proxy for maternal nutrition), TNFα and IL6 remained significant predictors (p < 0.05)." (PMID 30705878, 2018). "When these models were adjusted for maternal anemia, only TNFα and IL6 remained significant predictors of WAZ at final visit (p < 0.05)." (PMID 30705878, 2018). "A comparative gene expression analysis between M1 and M2 cells identified galectin-3 (Gal-3) and macrophage migration inhibitory factor (MIF) as novel M1-promoting factors, possibly acting synergistically and in concert with TNF-α during anemia development." (PMID 29497418, 2018). "These LT-α−/− mice were shown to exhibit during the middle stage of infection (days 10–28) a greatly reduced anemia compared with WT mice, which coincided with reduced TNF-α induction in LT-α−/− mice during this stage." (PMID 29497418, 2018). "IL-6 and tumor necrosis factor-α (TNF-α) are also important cytokines for the development of tumor-induced anemia." (PMID 29719631, 2018). "Many HLH-related and MCMV-induced cytokines are known to suppress hematopoiesis, amongst which IL-1β, IFN-γ and TNF-α, whereas IL-6 has the potency to specifically induce anemia." (PMID 29258535, 2017). "Taken together, our data show that anti-TNF therapy significantly improves iron metabolism and, subsequently, anaemia in IBD." (PMID 28191453, 2017). "Exploratory literature indicates altered pro-inflammatory makers IL-6, IL-8, TNF-α, treatment-induced anaemia, hypoalbuminemia, and a reduction in lean muscle mass are associated with the prevalence of CRF." (PMID 28895922, 2017). "In fact, numerous in vitro studies have illustrated the central role of tumor necrosis factor-alpha (TNF-α) in the pathogenesis of anemia." (PMID 27142617, 2016).
anemia (continued). "Taken together, these data prove that TNF plays a role in the pathogenesis of anemia in IBD through blocking the DMT1 expression." (PMID 26572590, 2015). "It was reported that over-expression of certain cytokines (TNF-α, among them) shortened the red blood cells survival, suppressed the erythroid progenitor cells and impaired iron utilization in cancer related anemia." (PMID 26011631, 2015). "IL-6, together with TNF-α, is an inflammatory cytokine critically involved in chronic disease ́ anemia, the major reason for the low hemoglobin levels in RA patients." (PMID 26177310, 2015). "For example, we recently showed in the same Nigerian population, that pro-inflammatory cytokines were more pronounced in SMA than in CM, a finding supported by the fact that pro-inflammatory TNF-alpha has a role in anemia establishment." (PMID 24743550, 2014). "Animal mortality during the acute phase of T. cruzi infection has been associated with multiple factors, including parasite strain virulence, anemia, increased levels of TNF-α, and T-cell hyperactivity." (PMID 25165415, 2014). "This type of anaemia develops due to a chronic inflammatory reaction, characterized by increased concentrations of TNF-α, IL-1, or IFN-gamma, which inhibit the secretion of erythropoietin and availability of iron, essential for efficient erythropoiesis." (PMID 24692849, 2014). "Improvement of anemia after biologic therapies such as TCZ or TNF inhibitors has been reported previously in RA, and other inflammatory diseases such as Castleman's disease." (PMID 24878740, 2014). "Elevated TNF levels have been associated with LBW and anemia while IFNγ is thought to be a critical factor in protection against placental malaria." (PMID 24465935, 2014). "The clinical signs (febrile responses, thrombocytopenia and anemia) associated with acute EIA are mediated by pro-inflammatory cytokines, such as TNFα, IL-6, and TGFβ." (PMID 25390683, 2014). "It is also worth noting that stronger inhibition of hepcidin-25 and significantly greater improvement in RA-anemia were observed in patients treated with tocilizumab than in patients treated with TNF-α inhibitors throughout the observation period." (PMID 24286116, 2013). "In this study, we evaluated and compared the effects of IL-6 and TNF-α blocking therapies on anemia, disease activity, and iron-related parameters including serum hepcidin in RA patients." (PMID 24286116, 2013). "While IL-6 and INF-γ are known to suppress erythropoiesis, TNF and IL-10 are thought to contribute to the degree of anaemia in children with falciparum malaria." (PMID 23978045, 2013). "In our cohort, tocilizumab was more effective than TNF-α inhibitors for improving anemia and normalizing iron metabolism in RA patients by inhibiting hepcidin production." (PMID 24286116, 2013). "The pro-inflammatory state is an essential component of anemia or chronic disease, as TNF-α and IL-6 inhibit erythropoietin production in the kidney and the proliferation of bone marrow erythroid progenitor cells." (PMID 23472188, 2013). "Patients afflicted with malignancy often develop anemia, and some cytokines, particularly TNF-α,TGF-β,IFN-β, IL-1,are found increasing in many malignant diseases." (PMID 22925697, 2012). "This is supported by the observation that anaemia is increased in IL-10 knockout mice infected with Plasmodium chabaudi and reversed upon TNF neutralization." (PMID 22853732, 2012). "Moreover, inflammatorycytokines like tumor necrosis factor (TNF) and IL-1 directly suppresserythropoietic activity, further contributing to anemia." (PMID 40630438, 2025). "Indeed, TNF-α, IL-6, and IL-1 are thought to contribute to RA-anemia development by modulating iron metabolism and suppressing bone marrow erythropoiesis, particularly by affecting the serum hepcidin level." (PMID 40648921, 2025).